GOLPH3 (golgi phosphoprotein 3)
Diseases named in the same sentence as GOLPH3 in open-access papers (continued):
Sharing a sentence is not in itself a finding about the gene and the disease.
cancer (continued). "Golgi phosphoprotein 3 (GOLPH3), a documented oncogene possessing potent transforming capacity, is not only up-regulated in many tumors but also an efficient indicator of poor prognosis and more malignant tumors." (PMID 31921678, 2019). "In this study, 83.64% of the DCIS recurrences demonstrated high/low GOLPH3 expression in carcinoma cells, while only 10.91% of the DCIS without recurrence showed high/low GOLPH3 expression." (PMID 31921678, 2019). "As regards carcinoma cases, we found negative/weak GOLPH3 expression in 24 (31.6%) cases and 52 (68.4%) cases showed moderate/intense expression." (PMID 28983350, 2015). "In addition, most of the studies that proved a promotive role of GOLPH3 on Akt focused on cancer proliferation rather than migration, invasion, and EMT." (PMID 35190555, 2022). "The clinical value of the serum GOLPH3 concentration in other cancers has not been reported." (PMID 33680216, 2021). "Because cancer has deep roots in multicellular evolution, studying the evolution of the GOLPH3 gene family in non-model species represents an opportunity to identify new model systems that could help better understand the biology behind this group of genes." (PMID 34127736, 2021). "The glycosylation of EGFR in HeLa cells is not affected by the levels of GOLPH3, and the consequence in other cancer cell lines is unknown." (PMID 33238647, 2020). "However, it has not been elucidated how the level of GOLPH3 expression impacts the activity of the mTOR-signaling pathway, and whether this contributes in different types of cancer cells to the same mechanisms that lead to malignancy." (PMID 30779783, 2019). "In such a case, enhanced GOLPH3 immunoreactivity in CAFs might be a potential marker for normal fibroblasts or early stage CAFs, which do not exhibit genetic aberrations or metabolic changes (e.g., increased production of cancer-promoting MMPs) typical for fully developed CAFs." (PMID 27706081, 2016).
tumor (79 papers, 2012 to 2025). "This analysis revealed a significant association of GOLPH3 with processes critical for tumor development and progression, potentially influenced by BPA." (PMID 38828452, 2024). "GOLPH3 has long been identified as an oncogene, implicated in advanced tumor stages, metastasis and poor patient outcomes." (PMID 37508488, 2023). "Independent reports demonstrated that GOLPH3 overexpression in PCa tissues is linked to higher Gleason grade, advanced pathological tumor stage, the presence of metastasis, worst overall survival and the state of the lymph nodes." (PMID 36387263, 2022). "In CRC, previous researches demonstrated that GOLPH3 overexpression was significantly associated with tumor invasion depth, lymph node metastasis, distant metastasis and advanced stages." (PMID 35372504, 2022). "Previous studies report that aberrant expression of GOLPH3 is highly associated with advanced tumor stage and vascular invasion in HCC." (PMID 35073936, 2022). "In our study we observed a statistically significant correlation between the presence of macronucleoli and increased number of nucleoli (polynucleolization) and decreased expression of GOLPH3 protein in tumor-associated macrophages (TAMs)." (PMID 29284501, 2017). "Single factor survival analysis indicated that lymphatic metastasis status, tumor invasion depth, and GOLPH3 expression were associated with 5 year-DFS and OS." (PMID 27634904, 2016). "The 148 cases included 77 with high GOLPH3 expression (52.03%), which was associated with tumor invasive depth and lymphatic metastasis." (PMID 27634904, 2016). "Recent studies identified a role for GOLPH3 in regulating various biological processes during tumorigenesis and GOLPH3 has been associated with the progression and outcome of many tumor types." (PMID 22905766, 2012). "GOLPH3 may thus be applied as a novel tumor marker for GC and CRC and has a higher diagnostic efficacy when combined with CEA and CA19-9 detection." (PMID 33680216, 2021). "In addition, gefitinib treatment caused a significant decrease of tumour volume both in the vector and GOLPH3 over‐expression groups." (PMID 31094020, 2019). "A statistically significant correlation was demonstrated between the presence of macronucleoli and increased number of nucleoli (polynucleolization) and decreased expression of GOLPH3 protein in tumor-associated macrophages (p = 0.034 and p = 0.042, respectively)." (PMID 29284501, 2017). "In addition, high GOLPH3 expression was associated with tumor differentiation (P = 0.011), increased serum CEA (P = 0.014), tumor invasion depth (T staging) (P = 0.029) and lymphatic metastasis (P = 0.037), but not with gender, age and tumor location." (PMID 27634904, 2016). "Importantly, several tumor types show overexpression of GOLPH3, which is associated with tumor progress and poor prognosis." (PMID 27123979, 2016). "Our study shows that the distinct association between GOLPH3 and tumor invasiveness may have therapeutic and prognostic implications." (PMID 26375441, 2015). "Thus, the detection of overexpressed GOLPH3 in cN0 oral tongue cancer should identify high-risk tumor phenotypes that require more aggressive primary surgery or adjuvant treatment following surgery." (PMID 22905766, 2012). "In addition, an increase om GOLPH3 in tumor-associated macrophages (TAMs) has been observed." (PMID 36142273, 2022). "In vivo, suppression of GOLPH3 expression inhibited tumor growth and increased apoptosis within the tumor microenvironment." (PMID 39944595, 2025). "In our study, we comprehensively investigated GOLPH3 expression in PCa cells from primary tumor tissues and metastatic lymph nodes." (PMID 37790749, 2023). "GOLPH3 promotes tumor cell proliferation, survival, migration and invasion via various mechanisms including activating the PI3K/Akt/mTOR signaling pathway as well as altering Golgi morphology and vesicular trafficking." (PMID 37508488, 2023).
tumor (continued). "The GOLPH3 complex plays an essential role in driving tumor progression through various mechanisms, one being its regulation of Golgi glycosylation—essential in promoting cancerous traits and progression." (PMID 37508488, 2023). "According to studies, GOLPH3 is important for proliferation, differentiation, and metastasis of tumor cells in various types of tumors." (PMID 36967990, 2023). "Golgi phosphoprotein 3 (GOLPH3) has been shown to promote tumor progression in a variety of gastrointestinal malignancies." (PMID 37081882, 2023). "We examined GOLPH3 expression in PCa cells from primary tumor and, as the first, also in metastatic lymph nodes to assess its potential as a new risk factor for PCa progression." (PMID 37790749, 2023). "At 1 week after injection, in the regular culture medium group, the number of disseminated tumor foci was elevated in the zebrafish tail region in the GOLPH3-overexpressing model compared with the number in the corresponding control." (PMID 35190555, 2022). "Within a week post-injection, increased numbers of disseminated tumor foci were observed in the zebrafish tail region in the GOLPH3-overexpression group compared with the numbers seen in the corresponding control group." (PMID 35190555, 2022). "A growing body of research has demonstrated that overexpression of GOLPH3 contributes to tumorigenesis and tumor metastasis." (PMID 35372504, 2022). "In the 25 μM CQ-cultured group, the number of disseminated tumor foci was decreased in both the GOLPH3-overexpression and control models." (PMID 35190555, 2022). "GOLPH3 overexpression mediates tumorigenesis by a sustained and enhanced mTOR signaling and provides a prognostic biomarker of tumor progression." (PMID 36142273, 2022). "Tumor volume and weight decreased in GOLPH3 knockdown group and sorafenib-treated groups compared with the control group." (PMID 35073936, 2022). "Golgi Phosphoprotein 3 (GOLPH3) was reported to promote tumor progression by regulating the transport of cell surface receptors." (PMID 35874843, 2022). "AUC for GOLPH3 was 0.845, which shows that these gene is useful to distinguish between tumor tissue and NAT." (PMID 36387263, 2022). "GOLPH3 is a significant contributor to the regulation of tumor cell proliferation, migration and chemoresistance." (PMID 35372504, 2022). "For this reason, we analyzed a combination of genes and miRNAs (hsa-miR-133a-3p, miR-1-3p, GOLPH3 plus JUP) as a possible biomarker panel to distinguish between tumor tissue and NAT." (PMID 36387263, 2022). "Findings from in vivo nude mice experiment showed that sorafenib administration and GOLPH3 knockdown decreased tumor growth and angiogenesis independently." (PMID 35073936, 2022). "Xenograft tumor model in nude mice were generated using MHCC-97H cell lines ectopically expressing GOLPH3 shRNA or control cells to explore the effects of GOLPH3 on tumor growth and sorafenib resistance in vivo." (PMID 35073936, 2022). "A total of 62% of patients (44 out of 71) with low expression levels of GOLPH3 showed tumor down-staging after nCRT; in contrast, only 43% (33 out of 77) with GOLPH3 overexpression in tumor tissue showed down-staging after nCRT (p = 0.020)." (PMID 35682714, 2022). "The DNA damage response triggered by clinical therapies, which protects tumour cells from apoptosis, is regulated by GOLPH3." (PMID 34195689, 2021). "GOLPH3 overexpression is correlated with tumor stage, which is an adverse clinicopathological characteristic of CRC." (PMID 34807928, 2021). "Compelling evidence demonstrates that tumor cells gain metastatic capacity through a GOLPH3-dependent Golgi membrane dispersal process which enhances vesicular release." (PMID 34055798, 2021). "When the data were combined separately, the high expression of GOLPH3 was significantly correlated with the clinicopathological parameters of the tumor." (PMID 34807928, 2021).
tumor (continued). "Meta-analysis revealed that GOLPH3 was found to be highly expressed in tumor tissues compared to that of adjacent colorectal tissues (OR, 2.63), and overexpression of GOLPH3 had significant relationship with advanced clinical stage (OR, 3.42)." (PMID 34807928, 2021). "Tumor-sphere formation and flow cytometry assays demonstrated that GOLPH3 overexpression enhances a stem cell-like phenotype of NSCLC cells." (PMID 34671013, 2021). "Other than the morphological effect on the Golgi, recent studies provided evidence that overexpression of GOLPH3 exerts its tumor-promoting activities via enhancing the production of specific growth-inducing glycosphingolipids (GSL)." (PMID 34055798, 2021). "We then analyzed the differences between the survival curves of patients with high and low GOLPH3 expression in subgroups of clinical stage and tumor-node metastasis (TNM) classification." (PMID 34671013, 2021). "It was reported that high GOLPH3 expression promoted tumor growth and metastasis-related protein secretion." (PMID 34497755, 2021). "In CRC, high GOLPH3 expression significantly correlates with poor patient survival and high tumor recurrence." (PMID 33670106, 2021). "To explore the role of GOLPH3 in promoting a tumor stemness phenotype in NSCLC cells in vivo, we injected A549 cells (1 × 106, 1 × 105, 1 × 104 or 1 × 103) mixed with Matrigel subcutaneously into the inguinal folds of BALB/c nude mice." (PMID 34671013, 2021). "A subcutaneous tumor formation model confirmed that GOLPH3 overexpression increased the tumorigenicity of NSCLC cells." (PMID 34671013, 2021). "This study demonstrated that the overexpression of GOLPH3 was found to be positively correlated with tumor stage, which is an adverse clinicopathological characteristic of CRC." (PMID 34807928, 2021). "Although the contribution of GOLPH3 to tumor growth and metastasis is well-supported; molecular pathways linking GOLPH3 to its oncogenic signaling are yet to be mapped in PDAC." (PMID 33134174, 2020). "Previous studies illuminate that GOLPH3 is a oncogene, which facilitates the occurrence and development of multiple signal transduction pathways and cell processes within some tumor types." (PMID 32307911, 2020). "The tumor volume of GOLPH3 shRNA group was significantly reduced compared with those in the vector group (p < 0.05)." (PMID 33134174, 2020). "The results revealed that depletion of GOLPH3 significantly suppressed tumor growth in the nude mice." (PMID 33134174, 2020). "BALB/c nude mice were used to assess tumor growth inhibition of BXPC3 cells stably transfected with GOLPH3 short hairpin RNA." (PMID 33134174, 2020). "In these cells, GOLPH3 depletion led to the reduction of the cytoplasmic tyrosine kinase FAK (focal adhesion kinase) autoactivation; thus, in the tumor line, overexpression of GOLPH3 would promote metastasis formation through FAK upregulation." (PMID 32023813, 2020). "Firstly, the GOLPH3 promoter region is detected, whose transcriptional factors or regulatory factors regulate tumor development and progression." (PMID 32307911, 2020). "Meanwhile, the tumour derived from GOLPH3 over‐expression cells was larger than that derived from vector cells, indicating that GOLPH3 promoted tumour growth." (PMID 31094020, 2019). "By counting the metaphase cells (mitotic index), we found that the percentage of metaphase cells of tumours derived from GOLPH3 over‐expression cells was 40.5% higher than that of vector group." (PMID 31094020, 2019). "In our system, after gefitinib treatment, there was only one in seven mice exhibited tumour in GOLPH3 over‐expression group, while every mouse bore tumour in the control group." (PMID 31094020, 2019). "Experimental data shows that overexpression of GOLPH3 leads to transformation of primary cells and to tumor growth enhancement." (PMID 30779783, 2019).
tumor (continued). "In our system, we found that the percentage of cleaved caspase‐3–positive cells in the tumours derived from GOLPH3 over‐expression group was lower than that derived from vector cells, indicating that GOLPH3 inhibited tumour cell apoptosis." (PMID 31094020, 2019). "Conversely, the knocking down of GOLPH3 in GOLPH3-overexpressing tumor cells reduces tumorigenic features, such as cell proliferation and cell migration and invasion." (PMID 30779783, 2019). "The tumour formation rate significantly decreased in GOLPH3 over‐expression group, implying that over‐expression of GOLPH3 enhanced the anti‐tumour effect of gefitinib in vivo." (PMID 31094020, 2019). "Next, we found that the percentage of Ki67‐positive cells in the tumours derived from GOLPH3 over‐expression cells was 54.54% higher than that of vector group." (PMID 31094020, 2019). "Six studies 16, 24-27, 29, comprising of 765 NSCLC patients, reported data concerning the expression of GOLPH3 in different degree of tumor differentiation in NSCLC patients." (PMID 31737112, 2019). "On the other hand, a remarkable early finding showed that in a set of tumor types the overexpression of GOLPH3 enhances the activity of the mTOR-signaling pathway." (PMID 30779783, 2019). "We have aimed to evaluate the contribution of GOLPH3 overexpression in the malignant phenotype of different types of tumor cells." (PMID 30779783, 2019). "Accordingly, inhibition of mTOR by rapamycin in cells that overexpress GOLPH3 results in detrimental effects on cell survival, cell proliferation, tumor growth, and cell migration and invasion." (PMID 30779783, 2019). "Consistently, after gefitinib treatment, tumours derived from GOLPH3 over‐expression cells exhibited lower Ki67‐positive and higher cleaved caspase‐3–positive cells than control tumours." (PMID 31094020, 2019). "It is very likely then that the effects of GOLPH3 on cell motility in different types of tumor cells is through affecting focal adhesion dynamics." (PMID 30779783, 2019). "GOLPH3 mRNA was over-expressed in HCC tumor tissues compared with that in corresponding adjacent normal liver tissues." (PMID 29914442, 2018). "Since GOLPH3 activates mTOR signaling through the phosphorylation of specific substrates of mTORC1 and mTORC2, increasing the sensitivity of tumor cells to rapamycin in vivo." (PMID 29996891, 2018). "The ability of GOLPH3 to promote HCC progression was further examined by using a xenograft tumor model." (PMID 29914442, 2018). "Data showed that the mRNA and protein expression of GOLPH3 were up-regulated in HCC tumor tissue and cell lines compared with those of control (P < 0.05)." (PMID 29914442, 2018). "For patients with low GOLPH3 expression, an increase in tumor invasion depth correlated with worse DFS (p=0.0186) and OS (p=0.0222)." (PMID 29285241, 2017). "We also assessed DFS and OS in patients with GOLPH3 expression as well as tumor invasion depth in patients with T1–T4 lesions." (PMID 29285241, 2017). "Conversely, GOLPH3 overexpression drives transformation of primary cell lines and enhances mouse xenograft tumor growth in vivo." (PMID 27123979, 2016). "Immunohistochemistry was used to assess GOLPH3 and mTOR (mammalian target of rapamycin) in tumor tissues." (PMID 27634904, 2016). "Experimental evidence shows that depletion of GOLPH3 abolishes transformation and proliferation of tumor cells in GOLPH3-overexpressing cell lines." (PMID 27123979, 2016). "We found unexpected differences that suggest that the function of GOLPH3 in different tumor cells is more complex than anticipated." (PMID 27123979, 2016). "Knockdown GOLPH3 expression resulted in a significant decrease in the tumor volume and weight as measured at the end of the experiment at day 40 when compared with Lv-shRNA-NC mice (P < 0.001)." (PMID 26375441, 2015).